CTNNA1 (catenin alpha 1)
Diseases named in the same sentence as CTNNA1 in open-access papers (continued):
Sharing a sentence is not in itself a finding about the gene and the disease.
metastatic cancers (1 paper, 2019). A carcinoma which has spread from the original site of growth to another anatomic site. "Since the pathways such as PI3K (AKT) and MAPK are significantly upregulated in metastatic cancers, we performed the Western blot to see the effect at a protein level after intracellular delivery of CTNNA1 and CTNNB1 siRNAs using CA nanoparticles in 4T1 cells." (PMID 31269666, 2019).
neuroblastoma (1 paper, 2019). Neuroblastoma (NB) is the most common solid, extracranial childhood tumor. "Our analyzed results also showed that there was a trend of correlation between CTNNA1 expression and survival in neuroblastoma within the datasets in R2 platform, suggesting a potential suppressive role of CTNNA1 in neuroblastoma." (PMID 31489113, 2019). "The exact mechanism of how CTNNA1 confers survivability in neuroblastoma will be investigated in the future study." (PMID 31489113, 2019). "We analyzed the relationship between CTNNA1 and CTNNA2 expression and patient prognoses in large, independent cohorts featuring all stages of neuroblastoma." (PMID 31489113, 2019). "We found that CTNNA1 and CTNNA2 had higher expressions, while CTNNA3 had consistently lower expression in both Wolf and Seeger datasets from patients with neuroblastoma." (PMID 31489113, 2019).
pneumonia (1 paper, 2022). An acute, acute and chronic, or chronic inflammation focally or diffusely affecting the lung parenchyma, caused by an infection in one or both of the lungs (by bacteria, viruses, fungi, or mycoplasma.). "Results suggested that 5 proteins with greater node degrees [i.e. catenin beta-1 (CTNNB1), integrin beta-1 (ITGB1), catenin alpha-1 (CTNNA1), dynamin-2 (DNM2), Keratin, type I cytoskeletal 19 (KRT19)] might function as crucial players in pneumonia-related bacterial infection in FMD." (PMID 36387401, 2022).
renal cell carcinoma (1 paper, 2023). "These 27 CTTs including 8 genes CTNNA1, PSMB6, PSMD12, SESN2, SLC22A2, UBE2J2, and NAE1 appeared in the SL pairs of renal cell carcinoma in previous literature studies." (PMID 38074121, 2023).
signet ring cell carcinoma (1 paper, 2021). A usually aggressive, poorly differentiated invasive adenocarcinoma characterized by the presence of malignant glandular cells in which the nucleus is pressed to one side by the presence of intracytoplasmic mucus. "Except for one patient, histological type of the rest of mutation-harboring patients was signet ring cell carcinoma, and only one HDGC patient had CTNNA1 mutation." (PMID 33868605, 2021).
skin melanomas (1 paper, 2021). "Many of them were previously appreciated in the genome of skin melanomas (e.g., MITF, NOTCH2, PD-L1 and JAK2 amplifications, or CDKN2A deletions); however, the CNAs in genomic locations harboring PAX5, ETS1, BCL7, RAD51, APAF1, FOXO3 and CTNNA1 are novel." (PMID 33779796, 2021).
systemic sclerosis (1 paper, 2023). A chronic disorder, possibly autoimmune, marked by excessive production of collagen which results in hardening and thickening of body tissues. "DNMT3A was found to be hypermethylated and underexpressed in systemic sclerosis microvascular endothelial cells, whereas CTNNA1 was found to be hypomethylated." (PMID 37039566, 2023).
tumor (56 papers, 2009 to 2025). "The alpha-E-catenin protein encoded by CTNNA1 plays an important role in cell adhesion and becomes a tumor suppressor gene after connecting with the plasma membrane calcium-binding proteins and intracellular actin filaments." (PMID 41378303, 2025). "The IHC showed loss of catenin alpha-1 expression in the tumor cells and preserved catenin alpha-1 expression in the normal gastric epithelium of the CTNNA1 variant carrier." (PMID 37686589, 2023). "The mutational profile of the CTNNA1 germline mutated tumour encompassed somatic mutations in RHOA, a specific DGC and PCC‐NOS gene, and in ARID1A and PIK3CA, genes transversally mutated in both DGC and IGC." (PMID 33724653, 2021). "Like CDH1, CTNNA1 is involved in intercellular adhesion and is a suspected tumor suppressor and susceptibility gene for DGC." (PMID 33868605, 2021). "Although the CTNNA1 protein functions to suppress tumor cell invasiveness, mutated CTNNA1 has been shown to be involved in GI tract cancer initiation." (PMID 34359854, 2021). "CTNNA1 plays an important role in intercellular adhesion, being a suspected tumor suppressor in several cancers and a susceptibility gene for DGC." (PMID 33868605, 2021). "Among genes deleted, tumour suppressor CTNNA1 (A1 105–124 Mb, human homologue in HSA 5q) is implicated in cell-cell adhesion maintainance and regulation of multiple signalling pathways in human cancer." (PMID 31969654, 2020). "Downregulation or loss of human α-catenin gene (CTNNA1) expression is seen in many cancer cell lines and primary cancer tissues, and α-catenin is recognized as a putative tumor suppressor." (PMID 28881822, 2017). "CDH1, MLLT4 and CTNNA1 were deleted in 29, 7 and 1 tumours, respectively, and harboured inactivating mutations in 169, 20 and 4 tumours, respectively." (PMID 27161491, 2016). "Since FAs maturation mediated by UBE2O-catalyzed CTNNA1 ubiquitylation could hypothetically reduce cell migration, it is possible that the tumor-inhibiting properties of UBE2O are linked to this function." (PMID 40983751, 2025). "While the function of CTNNA1 protein may include suppression of invasiveness of tumor cells, mutated CTNNA1 may be involved in induction of GI tract cancer." (PMID 33827580, 2021). "All the coding exons and intronic boundary regions of the CTNNA1 gene were successfully amplified using PCR in all patients, and DNA sequencing of the amplified PCR products showed 10 variants in the CTNNA1 gene of the tumor samples, among which one synonymous alteration was reported previously." (PMID 33868605, 2021). "As CTNNA1 was known to have tumour suppressor behaviour across multiple tumour types, here we classify the European-specific pLoF CTNNA1 TRA as a PP-SV." (PMID 38947031, 2024). "The precise mechanism of CTNNA1 in most cancers remains uncertain; hence, additional pre-clinical studies of CTNNA1 are warranted for potential early tumor diagnosis, prognosis, and treatment." (PMID 36741258, 2023). "CTNNA1 inhibited the transcription of genes related to tumor cell invasion by disrupting the binding of β-catenin-Tcf complex to DNA and suppressing the invasion of tumor cells." (PMID 36741258, 2023). "We identified three tumor suppressors: CTNNA1 (C772 and vicinal cysteine C767), GRIN2A (C320 and proximal C87), and CBFB (C25 and proximal C124)." (PMID 37085483, 2023). "KCL622 and KCL625 (both IC-NST) displayed CTNNA1 focal deep deletions in CSF cfDNA, while CTNNA1 had neutral copy number status in matched primary tumours." (PMID 37973922, 2023). "In many malignancies, CTNNA1 inhibits adhesion, invasion, and induces apoptosis of tumor cells by promoting or collaborating with CDH1 or inhibiting Wnt pathway." (PMID 36741258, 2023). "CTNNA1 can disrupt the interaction between the β-catenin-Tcf complex and DNA in vitro, which inhibits the transcription of genes involved in tumor cell invasion 17, suggesting that CTNNA1 and the Wnt pathway are germane." (PMID 36741258, 2023).
tumor (continued). "CTNNA1 has been fully established as a tumor suppressor that inhibits proliferation and invasion of various cancers." (PMID 36829181, 2023). "Tumor-derived mutations, for instance, mutations of CDH1 and CTNNA1 which are commonly detected in hereditary diffuse GC, are detected by next-generation sequencing." (PMID 36302755, 2022). "Of note, we identified somatic mutations in the promoter region and promoter methylation of CTNNA1 (α- catenin) in two tumours." (PMID 35053458, 2022). "Consistently, we found the downregulation of N-cadherin (CDH2) and α-catenin (CTNNA1) genes in the tumor mass of TG-hLH-R-frt-200 mouse, according to what occurs in human ECs35." (PMID 33893331, 2021). "Catenin Alpha (CTNNA1 and CTNNA2) expression was also down-regulated in cancerous tissues, which was consistent to well-reported tumor-suppressor functions of CTNNA1 and CTNNA2 in various cancers." (PMID 33335165, 2020). "Analysis of both our CRC cohort and R2 genomics expression datasets showed the downregulation of CTNNA1, HIGD2A and MIER3 (also in association with the severe features of the tumor), but also an evident positive correlation of expression with LINC00483." (PMID 33552987, 2020). "In human α-catenin family, CTNNA1 (α-E-catenin) is expressed ubiquitously in normal tissues, and it has been shown to regulate tumor initiation and have a suppressive role in tumor progression of intestinal tumorigenesis." (PMID 31489113, 2019). "In summary, the present study has suggested pseudogene CTNNAP1 is a potential tumor suppressor participating in CRC pathogenesis by competing with the parent gene CTNNA1 for microRNA-141." (PMID 27487124, 2016). "We further investigated the effects of overexpression of either CTNNA1 as well as CTNNAP1 on tumor growth in vivo." (PMID 27487124, 2016). "Beyond its role in adhesion regulation, CTNNA1 has been identified as a tumor suppressor." (PMID 40983751, 2025). "Therefore, CTNNA1 inhibits tumor metastasis most likely, at least partly, through the inhibition of EMT." (PMID 36741258, 2023). "CTNNA1 is highly expressed in DLD-1 cells with phosphor-/dephosphorylatable K-Ras, a necessary phenotype for maintaining epithelioid morphology and tumor growth, which may be associated with maintaining cell polarization and cell invasion." (PMID 36741258, 2023). "Parallel DNA sequencing of four tumor samples reveals two overlapping deletions on chromosome 5 in all three tumor samples, including CTNNA1, suggesting that CTNNA1 deletion may be involved in metastasis." (PMID 36741258, 2023). "A CTNNA1 deletion in tumor tissues and subsequent metastatic lesions is consistent with this." (PMID 36741258, 2023). "Whilst the function of this non-coding mutation upstream of the TSS region of CTNNA1 is unknown, this may highlight an additional inactivation mechanism of CDH1 mediated through CTNNA1 in the EcadhetILC tumours." (PMID 35053458, 2022). "Several studies have shown the tumor suppressor role of CTNNA1 in different tumors." (PMID 33552987, 2020). "The nonmutated gene product of CTNNA1 can function as a tumor invasion suppressor, but mutation is associated with gastrointestinal tract and other cancers." (PMID 30915033, 2019). "Similar to PKP1, CTNNA1, catenin cadherin-associated protein, alpha 1 (GeneBank: 1495) and AJAP1, adherens junctions associated protein 1 (GeneBank: 55966) expression levels are correlated with advancing tumor stage and inversely related to cell proliferation." (PMID 29052507, 2017). "Moreover, gain-of-function approaches showed that overexpression of CTNNAP1 or CTNNA1 significantly inhibited cell proliferation and tumor growth in vitro and in vivo by inducing G0/G1 cell cycle arrest." (PMID 27487124, 2016). "Several studies have assessed the tumor suppressive role of CTNNA1 in various tumors." (PMID 27487124, 2016). "Among the risky genes, CTNNA1, P4HB, and LMAN2 are associated with tumor development." (PMID 24871302, 2014).
tumor (continued). "In fact, we found several proteins possibly involved in actin cytoskeleton organization and cell-cell junction assembly, including talin-1, ezrin, plastin-3, fascin, catenin alpha-1, filamins A and B to be up-regulated in tumor tissues compared to control tissues." (PMID 24858105, 2014). "Additionally, some DGC patients tested negative for CDH1/CTNNA1 gene but had pathogenic variants in related tumor susceptibility genes, such as BRCA2, ATM, SDHB, PRSS1, MSR1, STK11, and PALB2." (PMID 37393258, 2023). "Of note, no copy number loss of CTNNA1 was observed in any tumour." (PMID 35053458, 2022). "Among them, CTNNA1, encoding α-catenin, has been shown to have tumor-suppressive functions in E-cadherin-negative BLBC, which suggests that MATR3 may also function as a tumor suppressor gene but its role in cancer remains elusive." (PMID 32977861, 2020). "Furthermore, gain-of-function assays were further explored that pseudogene CTNNAP1 could act as a ceRNA to increase CTNNA1 gene expression through competition for microRNA-141, subsequently inhibiting cell proliferation and tumor growth." (PMID 27487124, 2016). "By contrast, module 2 and 3, which were only downregulated in EGF-stimulated SHP2WT cells, contained several tumor suppressors, such as NRG1, MAP3K1, CAVIN3, EPHA3/7, CTNNA1/3, and NOTCH3." (PMID 40631144, 2025). "The allelic pseudogene of CTNNA1, CTNNAP1, competes with endogenous RNA (miR-141) to regulate CTNNA1 expression, which inhibits tumor growth and cell proliferation in the G1 or G0 phase of cell division in vitro and in vivo." (PMID 36741258, 2023). "Thus, CTNNA1 may act as a tumor suppressor gene by interacting with miRNAs." (PMID 36741258, 2023). "(b) Plot shows quantification of A431 tumour growth with the indicated manipulations of MMP14 and CTNNA1." (PMID 36892272, 2023). "Aside from CTNNA1, CTNNA2, and CTNNB1, there was low expression of most catenins in the tumor samples (P < 0.001) compared with the controls." (PMID 37924160, 2023). "(c) Table shows quantification of mice with primary tumours and mice with lymph node metastases when injected with A431 cells with the indicated manipulations of MMP14 and CTNNA1." (PMID 36892272, 2023). "(a) H&E images are shown on tumours growing in the ears of mice with the indicated manipulations of MMP14 and CTNNA1." (PMID 36892272, 2023). "Among the proteins with lower abundance in ATGL-KO spheroids, we identified catenin alpha-1 (CTNNA1, P35221), a tumor suppressor known to be downregulated in a number of human cancers." (PMID 33992777, 2021). "In addition, mutation of one of the catenin genes, CTNNA1, which functions as a tumor suppressor in normal conditions, leads to susceptibility to gastrointestinal tract cancers, and mutation of the other catenin gene, CTNNA2, is associated with tumor invasiveness." (PMID 31600974, 2019). "CTNNA1, a multifunctional protein that localizes at both the plasma membrane and the cytosol, plays crucial roles in actin dynamics regulation, cell-to-cell and cell-to-the extracellular matrix (ECM) adhesions and tumor suppression." (PMID 40983751, 2025). "For KCL658 and KCL650, however, no primary tumour was available for sequencing to determine the timing of CTNNA1 aberration." (PMID 37973922, 2023). "However, the growth and lymph node metastasis of MMP14 o.e./CTNNA1 KO cells were reduced compared to the MMP14 o.e. cells, indicating that the tumour promoting effect of elevated MMP14 levels depends on cell-cell adhesion." (PMID 36892272, 2023). "Notably, three members from the catenin super family, CTNNA1, CTNNA2, CTNNA3, were found to be dysregulated in tumor tissues." (PMID 36361574, 2022). "Silencing of genes involved in cell adhesion may lead to tumor aggressiveness and tumor progression, as was shown for CD97, CTNNA1, DLC1, and HAPLN2 genes in which hypermethylation was associated with poorer survival of patients with ovarian cancer." (PMID 33921911, 2021).
tumor (continued). "CTNNA1 and MIER3 have a well-known tumor suppressor function." (PMID 33552987, 2020). "Intravenous delivery of CTNNA1 siRNA with CA nanoparticles significantly reduced tumor volume in the initial phase of the study, while siRNAs targeting CTNNB1, TLN1, VCL, PXN, and ACTN1 genes significantly decreased the tumor burden at all time points." (PMID 31269666, 2019). "Taken together, the ability of CTNNA1 and CTNNAP1 to suppress cell proliferation and tumor growth indicates that CTNNAP1 and its cognate gene CTNNA1 may potentially play tumor suppressive roles in CRC." (PMID 27487124, 2016). "From the Human Tumor Metastasis RT-PCR array with ATAD2 siRNA-treated cells, we identified APC, ITGB3, FXYD5, ITGA7 and CTNNA1 (α-catenin), which are related to cell adhesion; among these, the expression of APC and CTNNA1 changed by at least 3-fold." (PMID 24552534, 2014). "We investigated CTNNA1, HIGD2A, and MIER3 expression in CRC biopsies compared to adjacent normal mucosa in order to confirm their downregulation in CRC observed by dataset screening: the three mRNAs showed a statistically significant downregulation in tumor tissues compared to normal mucosa." (PMID 33552987, 2020). "Furthermore, when intravenous delivery of CTNNA1 and CTNNB1 siRNAs loaded with CA nanoparticles was done in the 4T1 tumor bearing the Balb/c mice model, the reduced tumor volume compared to the CA nanoparticle treated controls indicated the role of these genes in tumorigenesis." (PMID 31269666, 2019). "Look and colleagues found that decreased CTNNA1 expression in CD34+CD38-CD123+Lin- cells from high risk del(5q) associated MDS or AML patients was associated with methylation of the CTNNA1 promoter, but not with point mutations of the residual allele in primary tumor cells." (PMID 19240791, 2009).